GNPDA1 (glucosamine-6-phosphate deaminase 1)
Description:
Catalyzes the reversible conversion of alpha-D-glucosamine 6-phosphate (GlcN-6P) into beta-D-fructose 6-phosphate (Fru-6P) and ammonium ion, a regulatory reaction step in de novo uridine diphosphate-N-acetyl-alpha-D-glucosamine (UDP-GlcNAc) biosynthesis via hexosamine pathway. Deamination is coupled to aldo-keto isomerization mediating the metabolic flux from UDP-GlcNAc toward Fru-6P. At high ammonium level can drive amination and isomerization of Fru-6P toward hexosamines and UDP-GlcNAc synthesis. Has a role in fine tuning the metabolic fluctuations of cytosolic UDP-GlcNAc and their effects on hyaluronan synthesis that occur during tissue remodeling. Seems to trigger calcium oscillations in mammalian eggs. These oscillations serve as the essential trigger for egg activation and early development of the embryo (By similarity).
Synonyms: GNPI; HLN; KIAA0060; GNPDA; GPI; GNP1
Tractability: Small molecule: a structure with a bound ligand is known; it has a high-quality binding pocket. PROTAC: ubiquitination databases record sites on it; its protein half-life has been measured.
Target class: Enzyme; Hydrolase
Gene: Protein-coding gene on chromosome 5 (141,991,749 to 142,013,057, reverse strand). Ensembl gene ENSG00000113552.
Subcellular location: Cytoplasm
Subcellular location (Human Protein Atlas): Vesicles; Golgi apparatus
Pathways (Reactome):
Metabolism: Glycolysis
Gene Ontology:
Molecular function: glucosamine-6-phosphate deaminase activity; protein binding; identical protein binding
Biological process: generation of precursor metabolites and energy; glucosamine catabolic process; UDP-N-acetylglucosamine biosynthetic process; N-acetylglucosamine catabolic process; N-acetylneuraminate catabolic process; single fertilization; carbohydrate metabolic process; N-acetylglucosamine metabolic process
Cellular component: extracellular exosome; cytoplasm; cytosol
Genetic constraint (gnomAD): Loss-of-function variants: 14 observed, 18.72 expected, observed/expected ratio (o/e) 0.75, 90% interval 0.49 to 1.17. The upper end of that interval is the gene's LOEUF score, 1.17, which puts it in group 5 of 6, group 1 being the genes least tolerant of losing a copy. Missense variants: 217 observed, 296.55 expected, observed/expected ratio (o/e) 0.73, 90% interval 0.65 to 0.82. Synonymous variants: 120 observed, 114.86 expected, observed/expected ratio (o/e) 1.04, 90% interval 0.9 to 1.22.
Homologues: Orthologues: chimpanzee GNPDA1 (100% identical), rabbit GNPDA1 (98% identical), mouse Gnpda1 (96% identical), pig GNPDA1 (96% identical), rat Gnpda1 (96% identical), guinea pig GNPDA1 (96% identical), dog GNPDA1 (95% identical), macaque GNPDA1 (90% identical), tropical clawed frog gnpda1 (90% identical), zebrafish gnpda1 (79% identical), Drosophila melanogaster Oscillin (69% identical), Caenorhabditis elegans T03F6.3 (64% identical). Paralogues in human: GNPDA2 (83% identical).
Diseases named in the same sentence as GNPDA1 in open-access papers:
GNPDA1 is named in the same sentence as 29 diseases in open-access papers, as found by Europe PMC text mining. Sharing a sentence is not in itself a finding about the gene and the disease. The quoted sentences say what the papers report.
hepatocellular carcinoma (7 papers, 2016 to 2025). A malignant tumor that arises from hepatocytes. "Several studies have revealed that GNPDA1 is one of the nine-gene amino acid metabolism-related risk signatures that are constructed to indicate the overall survival of hepatocellular carcinoma patients." (PMID 40278313, 2025). "A few studies have shown that GNPDA1 influences the development of several cancers, such as hepatocellular carcinoma, gastrointestinal cancer, ovarian cancer, and colorectal cancer." (PMID 40278313, 2025). "Forty-one years later, it was confirmed that GNPDA1 mRNA expression was significantly increased in hepatocellular cancer (HCC) tissues and hepatoma cell lines, and it is a hallmark of a poor prognosis." (PMID 39596123, 2024). "GNPDA1 is mainly related to glycolysis and amino acid metabolism; studies have shown that GNPDA1 is overexpressed in hepatocellular carcinoma." (PMID 36566175, 2022). "Whether a higher expression of GNPDA1 in hepatoma cells can increase HA synthesis, favoring pro-tumor effects, is still an open question." (PMID 39596123, 2024). "It has been reported that IDUA is involved in chondroitin sulfate/dermatan sulfate metabolism and glycosaminoglycan metabolism, and IDUA_GNPDA1 could be used as a beneficial prognostic factor in hepatocellular carcinoma." (PMID 36814419, 2023). "Therefore, GNPDA1 promotes hepatocellular carcinoma progression by inhibiting HCC cell apoptosis." (PMID 35747825, 2022).
colorectal cancer (4 papers, 2021 to 2025). A primary or metastatic malignant neoplasm that affects the colon or rectum. "Moreover, GNPDA1 was associated with protein upregulation and was noted to play a role in the biological processes underlying anti-cancer activity against colorectal cancer and gastrointestinal cancer." (PMID 40278313, 2025). "The GNPDA2 gene is associated with a greater body mass index and obesity, while colorectal cancer, hepatocellular, and other gastrointestinal malignancies show increased GNPDA1 protein levels; the latter is addressed in the next section." (PMID 39596123, 2024). "Elevated GNPDA1 expression levels are associated with poor prognosis in patients with HCC, pancreatic cancer and colorectal cancer." (PMID 33663535, 2021). "This study did not suggest a reason for this; the fact is that colon and colorectal cancer SW480 cells express both GNPDAs, mostly GNPDA1, and its increased expression seems to be protective against tumor progression." (PMID 39596123, 2024).
breast carcinoma (2 papers, 2024 to 2025). "The discovery that RNA and methyl-CpG binding are associated with the potential genes emphasizes that GNPDA1 is a potential biomarker of breast cancer development." (PMID 40278313, 2025). "Through a MethSurv analysis, GNPDA1 hypomethylation and SLC25A16 hypermethylation were associated with poor prognoses in terms of overall survival in breast cancer." (PMID 40278313, 2025). "Further, GNPDA1 and SLC25A16 were enriched in known targets of approved cancer drugs as potential genes associated with breast cancer." (PMID 40278313, 2025). "GNPDA1 overexpressed hypomethylation and SLC25A16 underexpressed hypermethylation in breast cancer cells were associated with poor prognosis in patients with breast cancer." (PMID 40278313, 2025). "This indicates that GNPDA1 is linked to several genes such as BRCA1 and RAD50 and is associated with DNA damage and breast cancer." (PMID 40278313, 2025). "First, GNPDA1 was strongly associated with “DNA damage_ATM activation by DNA damage (p = 4.282 × 10−06)”, “BRCA1 and BRCA2 in breast cancer (p = 6.950 × 10−04)”, and “DNA damage_ATM/ATR regulation of G2/M checkpoint: nuclear signaling (p = 8.093 × 10−04)”." (PMID 40278313, 2025). "Further, we found that GNPDA1 and SLC25A16 were enriched in known targets of approved cancer drugs as potential genes associated with breast cancer." (PMID 40278313, 2025). "Moreover, through a MetaCore functional enrichment analysis, GNPDA1 and SLC25A16 were associated with the BRCA1, BRCA2, and pro-oncogenic actions of the androgen receptor in breast cancer." (PMID 40278313, 2025). "According to the DNA methylation analysis in the current study, GNPDA1 and SLC25A16 in a single CpG serve as prognostic biomarkers of breast cancer." (PMID 40278313, 2025). "As a result of the gene list as input in MetaCore analysis, we discovered some interesting results regarding GNPDA1 and SLC25A16 in the development of breast cancer." (PMID 40278313, 2025). "The distribution of genetic changes for specific candidate genes revealed that GNPDA1 and SLC25A16 mRNA levels were elevated in approximately 5% of breast cancer samples." (PMID 40278313, 2025). "Our comprehensive study revealed that GNPDA1 and SLC25A16 have prognostic value in patients with breast cancer." (PMID 40278313, 2025). "According to our bioinformatics analysis results, GNPDA1 and SLC25A16 have much prognostic value—they play key roles in genetic alterations and signaling pathways in breast cancer." (PMID 40278313, 2025). "Using MetaCore, we examined the co-expressed genes for GNPDA1 and SLC25A16 from the cBioPortal and TCGA breast cancer data sets." (PMID 40278313, 2025). "The most interesting finding of the MetaCore analysis was the significant correlation between GNPDA1 and BRCA1 and BRCA2 in breast cancer cells." (PMID 40278313, 2025). "The result shows that breast invasive carcinoma (NOS) appears to have a much higher frequency of GNPDA1 and SLC25A16 (15,49%) than the other subtypes of breast carcinoma." (PMID 40278313, 2025). "GNPDA1 and SLC25A16 exhibited significant expression in breast cancer tissues based on UALCAN analysis, where they were overexpressed and underexpressed, respectively." (PMID 40278313, 2025). "According to the methylation levels, the cg00145118 of GNPDA1 and cg00203461 and the cg10590909 and cg16214034 of SLC25A16 had the highest prognostic value in patients with breast cancer (LR test p < 0.05)." (PMID 40278313, 2025). "Using the Methsurv web tool, a heat map demonstrated the significance scores of DNA methylation which predict expression levels of GNPDA1 and SLC25A16 in patients with breast cancer." (PMID 40278313, 2025). "GNPDA1 and SLC25A16 play important roles in the BRCA1, BRCA2, and pro-oncogenic actions of the androgen receptor in breast cancer development." (PMID 40278313, 2025).
head and neck squamous cell carcinoma (2 papers, 2019 to 2025). A squamous cell carcinoma that arises from any of the following anatomic sites: lip and oral cavity, nasal cavity, paranasal sinuses, pharynx, larynx, and salivary glands. "For example, a 7-mRNA signature (AATF, APP, GNPDA1, HPRT1, LASP1, P4HA1 and ILF3) of head and neck squamous cell carcinoma (HNSCC) shows a moderate predictive ability for 5-year OS (AUC for training set, 0.75; testing set, 0.66)." (PMID 31396442, 2019).
liver cancer (2 papers, 2021 to 2025). An epithelial or non-epithelial malignant neoplasm that arises from the liver. "Glucosamine-6-phosphate deaminase 1 (GNPDA1) and procollagen-lysine (PLOD2) are upregulated in liver cancer and promote tumor proliferation and migration, which are correlated with poor prognosis." (PMID 34557495, 2021).
Obesity (2 papers, 2018 to 2024). Accumulation of substantial excess body fat. "GNPDA1 is expressed in the brain to an even greater extent than GNPDA2; however, it is still unknown whether it plays any role in the metabolism of glucose in this organ in relation to obesity." (PMID 39596123, 2024).
colon cancer (1 paper, 2020). "From the literature survey, we found that TPK1 is an oncogene for colon cancer, and three genes (PTEN, GNPDA1 and PIK3CA) appear in head and neck cancer." (PMID 32269785, 2020).
lung adenocarcinoma (1 paper, 2025). A carcinoma that arises from the lung and is characterized by the presence of malignant glandular epithelial cells. "GNPDA1 continued to be significantly associated with lung adenocarcinoma." (PMID 41340014, 2025). "For the significant proteins identified in the observational analyses, Agrin (AGRN), CD5 antigen‐like (CD5L), glucosamine‐6‐phosphate isomerase 1 (GNPDA1), integrin beta‐2 (ITGB2) and neuronal‐specific septin‐3 (SEPTIN3) remained associated with lung adenocarcinoma in the two‐sample MR analyses." (PMID 41340014, 2025).
tumor (9 papers, 2016 to 2025). "There was a significant correlation between high expression of GNPDA1 and advanced tumor stage, N-stage, or G-grade, and it was associated with gender." (PMID 40419932, 2025). "The expression of GNPDA1 was also found to be closely linked to tumor grading, with G stage patients exhibiting significantly elevated expression levels." (PMID 40419932, 2025). "Understanding the role of GNPDA1 and its associated activation pathways is crucial in unraveling its impact on tumor regulation." (PMID 40419932, 2025). "This suggests a potential role for GNPDA1 in the immune response to tumors, highlighting its importance in tumor cells and immune cells." (PMID 40419932, 2025). "The relationship between the clinical data of 2 distinct level groups of GNPDA1, including gender, age, grading, and tumor TNM staging, was analyzed through data analysis, as depicted in the heatmap." (PMID 40419932, 2025). "In conclusion, GNPDA1 emerges as a key player in solid tumor development, exerting its influence on both tumor progression and immune cell function in the TME." (PMID 40419932, 2025). "On the basis of tumor stage indicators, we found that in more advanced tumors, GNPDA1 and SLC25A16 mRNA expression tended to have more statistical significance (middle)." (PMID 40278313, 2025). "GNPDA1 plays a crucial role in shaping the immune environment within tumor cells and has a significant impact on the prognosis of HNSCC patients." (PMID 40419932, 2025). "GNPDA1 expression was positively correlated with tumor malignancy (P < .05) and negatively correlated with patient prognosis (P < .05)." (PMID 40419932, 2025). "Analysis of single-cell sequencing data from the TICH database revealed high expression of GNPDA1 in tumor cells and immune cells." (PMID 40419932, 2025). "The findings revealed a consistent trend of elevated GNPDA1 expression levels across almost all tumor types." (PMID 40419932, 2025). "Kaplan–Meier survival analysis evaluated the relationship between GNPDA1 expression and advanced tumor stage, TNM stage, grading, and gender." (PMID 40419932, 2025). "GNPDA1 displayed a pro-tumor effect in HCC, and we would expect that, by exposing cancer cells to an anti-tumor drug, the expression/activity of GNPDA1 would be down-regulated." (PMID 39596123, 2024). "From our findings, three (GPR6, GRASP, JDP2) of the six validated genes of phase A are related to EMT and tumor migration; one validated gene (GNPDA1) links to the glycolytic pathway and glycosylation." (PMID 35563509, 2022). "Additionally, we found that more advanced tumor stages tended to have significantly higher GNPDA1 mRNA expression based on the clinical and pathological features of the tumor stage." (PMID 40278313, 2025). "In addition, the location of GNPDA1 in tumor cell and immune cell structures was identified by the tumor immune stromal cells helper database, and potential protein-interacting molecules of GNPDA1 were elucidated in the STRING database." (PMID 40419932, 2025). "GNPDA1 expression was enhanced in primary tumor cells compared to normal cells." (PMID 40278313, 2025). "In addition, the expression levels of GNPDA1 were compared between tumor tissue and normal tissue, as well as their respective paired normal tissues." (PMID 40419932, 2025). "Statistically significant differences (p < 0.05) were observed in the expression of GNPDA1 and SLC25A16 between the normal and tumor tissues (left)." (PMID 40278313, 2025). "The NUP85, HAX1, GNPDA1 and HDLBP protein levels were significantly elevated in tumor tissues compared to normal samples, while GPD1 was significantly down-regulated in tumor tissues." (PMID 33663535, 2021). "In addition, NUP85, HAX1, GNPDA1 and HDLBP exhibited elevated mRNA expression levels in GI tumor tissues when compared to the adjacent non-tumor tissues, whereas GPD1 expression was suppressed in GI tumor tissues compared to the non-tumor tissues." (PMID 33663535, 2021).
cancer (6 papers, 2016 to 2025). A tumor composed of atypical neoplastic, often pleomorphic cells that invade other tissues. "Age, a family history of cancer, and alcohol consumption were associated with GNPDA1 and SLC25A16 based on the current data set and the GEO data set." (PMID 40278313, 2025). "The HBP enzymes glucosamine-6-phosphate deaminases 1 and 2 (GNPDA1 and 2) turn GlcN6P back into Fru6P and ammonium, and have been implicated in cancer and metabolic diseases." (PMID 39596123, 2024). "The analysis of GNPDA1 expression in various types of cancer revealed significant upregulation in 17 out of 23 malignancies compared to normal tissues." (PMID 40419932, 2025). "These comparisons provided further insights into the role of GNPDA1 in cancer development and its potential as a biomarker for diagnosis or treatment." (PMID 40419932, 2025). "In summary, we identified and validated a glycolysis associated five-gene risk signature (NUP85, GPD1, HAX1, GNPDA1 and HDLBP) that can predict the OS of GI Asian cancer patients." (PMID 33663535, 2021). "While GNPDA1 has been detected in certain cancer cell lines, its specific role in tumorigenesis remains unclear." (PMID 40419932, 2025). "Moreover, the study examined the OS rates of patients with GNPDA1 expression in the 23 types of cancer under investigation." (PMID 40419932, 2025). "In conclusion, the role of GNPDA1 in cancer cells is currently unclear." (PMID 39596123, 2024). "Recently, evidence showing a clear relationship between GNPDA1 and some cancers was described." (PMID 39596123, 2024). "Glucosamine-6-phosphate isomerase 1 (GNPDA1) can catalyze the conversion of glucosamine 6-phosphate to fructose 6-phosphate and thereby increase the raw materials for glycolysis, which enhances cancer progression." (PMID 33663535, 2021). "By analyzing interactions with the GNPDA1 protein using the STRING database, researchers identified 4 key genes (GABPB1, CDK4, ADNP, and APH1A) that play important roles in cellular processes related to cancer." (PMID 40419932, 2025).
GI tumor (1 paper, 2021). "We identified five novel glycolysis-associated genes (NUP85, GPD1, HAX1, GNPDA1, and HDLBP) in GI tumor and normal tissues." (PMID 33663535, 2021).
GNPDA1 also shares sentences with these, for which no sentence is quoted: adenocarcinoma (1 paper); asthma (1); breast invasive carcinoma (1); cyst (1); disseminated candidiasis (1); head and neck cancer (1); Huntington disease (1); lung carcinoma (1); melanoma (1); ovarian carcinoma (1); pancreatic cancer (1); pouchitis (1); prostate carcinoma (1); small cell carcinoma (1); squamous cell carcinoma (1); systemic candidiasis (1); varicocele (1); viral infection (1).